SNORA36B (small nucleolar RNA, H/ACA box 36B)
Synonyms: ACA36b
Gene: Small nucleolar RNA gene on chromosome 1 (220,200,546 to 220,200,676, reverse strand). Ensembl gene ENSG00000222370.
Gene Ontology:
Biological process: RNA processing
Cellular component: nucleolus
Homologues: Orthologues: chimpanzee SNORA36B (100% identical), macaque SNORA36B (97% identical), rat Snora36b (91% identical), rabbit SNORA36B (90% identical), pig SNORA36B (89% identical), mouse Snora36b (89% identical). Paralogues in human: SNORA36A (88% identical), SNORA36C (88% identical).